CTSK (cathepsin K)
Diseases named in the same sentence as CTSK in open-access papers (continued):
Sharing a sentence is not in itself a finding about the gene and the disease.
breast carcinoma (51 papers, 2010 to 2025). "After a long period of time, cathepsin K inhibitors are now re-assessed in osteoclast-mediated bone resorption and re-evaluated for treatment of bone disease caused by metastasizing (breast) carcinoma cells." (PMID 41393280, 2025). "In breast cancer, a high expression of Osteopontin was associated with frequent osteolysis, inducing the expression of bone-resorbing proteases, cathepsin K, and MMP9." (PMID 36499741, 2022). "Given that cathepsin K is frequently upregulated in breast cancer and is associated with more invasive disease and increased risk of bone metastasis, it has become a clinical therapeutic target of interest." (PMID 26237063, 2013). "The expression of CTSK in breast cancer progression is also associated with other factors." (PMID 36005209, 2022). "Cathepsin K has also been associated with diseases, such as breast cancer and schizophrenia." (PMID 21794126, 2011). "Our findings suggest that TP inhibits NF-κB and ERK signaling pathways, reduces breast cancer-induced osteoclastogenesis, and decreases NFATc1, CTSK, and RANKL expression." (PMID 40444046, 2025). "To conclude, cathepsin K plays a major role in the metastatic spread of breast cancer cells to the bone." (PMID 36002710, 2023). "In a study on breast cancer, inhibition of cathepsin K restrained the adhesion, migration, and metastasis of cancer cells through integrin molecules and their downstream targets: MMP-9, PI3K, and the MAPK signaling pathway." (PMID 37398678, 2023). "CTSK has been shown to promote invasion and metastasis of breast cancer through direct degradation of the extracellular matrix (ECM) and promotion of angiogenesis or enhancing paracrine interactions." (PMID 37930479, 2023). "Increasing evidence provides insight into how breast cancer cells take advantage of yet another member of the cathepsin family, cathepsin K. Cathepsin K is an endopeptidase that functions in the lysosomal and extracellular environment." (PMID 36002710, 2023). "Breast cancer studies also acknowledged that CTSK activates pro MMP9 to produce MMP9 that potentiates migration of breast cancer cells to establish distant metastasis." (PMID 37198626, 2023). "Strong CTSK expression was noted in human breast cancers with primary and developing bone metastasis." (PMID 37198626, 2023). "It is reported that OC-derived bone sialoprotein promotes OC differentiation in an autocrine manner activated by CTSK, resulting in promoting the osteolytic metastasis of breast cancer." (PMID 36005209, 2022). "Beyond the osteoclasts, CTSK is highly expressed in various malignant tumors, such as breast carcinomas, lung cancers, melanomas, ovarian carcinomas, and prostate cancers." (PMID 36052250, 2022). "For instance, in animal experiments studying breast cancer, the intravenous inoculation of CTSK-expressing human B02 breast cancer cells resulted in the formation of bone metastases." (PMID 36005209, 2022). "Nowadays, CTSK has been involved in various cancers such as prostate cancer, breast cancer, bone cancer, renal carcinoma, lung cancer and other cancers." (PMID 36005209, 2022). "Cathepsin K–shRNA transfection has been demonstrated to downregulate Cathepsin K, inhibiting the proliferation and metastasis of breast cancer cells." (PMID 32927648, 2020). "Cathepsin K inhibitors suppressed breast cancer-mediated osteolysis and breast cancer cell invasiveness, and odanacatib (MK-0822), one of the cathepsin K inhibitors, decreased bone turnover markers in a phase II clinical trial of breast cancer bone metastasis." (PMID 32674405, 2020). "Another cathepsin K inhibitor, L-235 (L-006235), decreases breast cancer cell-induced osteolysis and tumor burden in the bone." (PMID 32674405, 2020). "Cathepsin K plays an important role in osteoclast-mediated bone destruction, and it is increased in breast cancer with bone metastasis." (PMID 32674405, 2020).
breast carcinoma (continued). "Cathepsin K from breast cancer cells activates osteoclasts, which promotes osteolytic bone metastasis, and cathepsin K from the bone marrow stromal cells promotes breast cancer bone metastasis by splicing and activating SPARC in breast cancer cells." (PMID 32674405, 2020). "Amongst several other cancer cell lines, CtsK expression was detected also in the MDA-MB-231 breast cancer cells." (PMID 32188406, 2020). "In summary, inhibition of CtsK reduced bone fracture rates and osteolysis, but also skeletal tumor burden, tumor volume and breast cancer invasion." (PMID 32188406, 2020). "In this study, we identified FOXF2 as another direct regulator of CTSK transcription and CTSK-mediated breast cancer bone metastasis." (PMID 31222004, 2019). "CTSK is ectopically expressed in breast cancer cells that metastasize to bone to promote tumor cell invasiveness and contribute to bone degradation." (PMID 31222004, 2019). "To provide clinical evidence validating the role of CTSK and the FOXF2-CTSK axis in breast cancer bone metastasis, we analyzed CTSK expression levels in metastatic tissues in bone and other organs based on the GSE14020 data set." (PMID 31222004, 2019). "Recently, RON kinase and Cathepsin K inhibitors have demonstrated a reduction in breast cancer induced osteolysis and skeletal tumor burden in preclinical and clinical studies." (PMID 29805773, 2018). "Here we correlate the epithelial-mesenchymal-like transition breast cancer cells and cathepsin K secretion with activation and aggregation of platelets." (PMID 26931461, 2016). "In breast cancer bone metastasis, inhibition of cathepsin K has dramatically reduced metastatic lesions." (PMID 23951042, 2013). "Expression of cathepsin K has been found in many malignancies, including prostate and breast cancers." (PMID 23918298, 2013). "Use of the cathepsin K inhibitor, odanacatib, was recently evaluated in women with breast cancer and metastatic bone disease." (PMID 26237063, 2013). "Expression of cathepsin K has been demonstrated in malignancies including primary prostate and breast cancer, both of which have a high propensity to metastasize to bone tissue." (PMID 23951042, 2013). "Cathepsin K expression has previously been reported in primary human breast tumors and their metastases, including breast cancer cells within bone metastatic lesions." (PMID 22621373, 2012). "The falcipain-1-similar cathepsin K is overexpressed in prostate and breast cancer and might be a likely and promising target for 4-HNE due to DHA treatment." (PMID 37508006, 2023). "Inhibition of cathepsin K may inhibit breast cancer bone metastasis by reducing the expressions of TNF-α, IL-6, and IL-1β." (PMID 37398678, 2023). "Therefore, it is plausible that CTSK has the ability to promote the invasion and migration of breast cancer cells via degrading ECM." (PMID 36005209, 2022). "Moreover, CTSK has also been described to be expressed by breast cancer and prostate cancer that metastasize to bone, where it functions in osteolysis that contributes to tumor invasiveness." (PMID 35372028, 2022). "In addition, studies have shown that CTSK is strongly expressed in human breast cancers with primary or developing bone metastases." (PMID 36005209, 2022). "Increasing reports have suggested that upregulated CTSK could be found in patients with breast cancer, giant cell tumors of bone, prostate cancer and many other types of epithelial-derived cell cancers." (PMID 36005209, 2022). "In addition, increased expression and activity of Cathepsin K have been reported in patients diagnosed with breast cancer, bone cancer, prostate cancer, and many other types of epithelial-derived cell cancers." (PMID 32927648, 2020). "Cathepsin K expression has also been found in normal bronchial epithelial cells, thyroid epithelial cells, synovial fibroblasts of patients with rheumatoid arthritis, breast carcinoma cells, osteoblast and chordoma." (PMID 32117071, 2020).
breast carcinoma (continued). "Moreover, inhibition of CtsK in bone metastasis of breast cancer has been shown to reduce bone resorption." (PMID 32188406, 2020). "Cathepsin K induces platelet dysfunction and affects signaling in breast cancer cells." (PMID 26931461, 2016). "Our finding that proMMP-9 and CTSK are secreted by both OCs and the metastatic breast cancer cell line MDA-MB-231 allude to a potential paradigm where the activation of proMMP-9 can occur through crosstalk between OCs resorptive pits and arriving breast cancer cells." (PMID 26219353, 2015). "Odanacatib (MK-0822, Merck) is a monoclonal antibody against cathepsin K and has been studied in women with breast cancer with bony metastases; again, cathepsin K may represent a potential therapeutic target." (PMID 22566752, 2012). "Importantly, cathepsin K expression is consistently higher within bone-residing breast cancer cells than in the primary tumor, suggesting that this enzyme has a central role in creating the necessary microenvironmental conditions for breast cancer cells to metastasize to bone." (PMID 36002710, 2023). "Thus, selective CTSK inhibitors may prevent the establishment and progression of breast cancer and prostate cancer in the bone, becoming a new treatment for advanced cancers." (PMID 36005209, 2022). "Besides breast cancer, it has been reported that the CTSK inhibitor could suppress the bone metastasis of advanced prostate cancer, and the CTSK inhibitor also diminished prostate cancer-induced bone lesions." (PMID 36005209, 2022). "Additionally, osteoclast differentiation and rheumatoid arthritis signaling pathways and related DEGs including FOS and CTSK may be involved in the development of bone metastasis from breast cancer." (PMID 30918839, 2019). "Interestingly, LIPUS treatment in co-culture system, which is closer to an in vivo setting, seemed to have a greater inhibitory effect on the osteolytic capacity of metastatic breast cancer cells, in particular for Trap and Ctsk expression and CTSK and MMP9 protein release." (PMID 30126457, 2018). "IL-20 upregulates CTSK and MMP-9 to promote the proliferation and migration of breast cancer cells in vitro." (PMID 36005209, 2022). "In vitro study, we found the protein expression level of CTSK was decreased in macrophages and PDLSCs after treatment with TC-ODN under inflammatory environment, and this effect was also found in breast cancer cells." (PMID 36386169, 2022). "This study showed that CtsK is involved in processing and trafficking of TRAP-isoforms in the TRAP-overexpressing MDA-MB-231 breast cancer cells." (PMID 32188406, 2020). "Breast cancer cells have been reported to secrete various adipokines, such as leptin, adiponectin, ATX, COX-2/PEG2, MMP, cathepsin K, TGF- β, IGF1 and VEGF (review)." (PMID 32674405, 2020). "The presence of a positive feedback connection in expression of TRAP and CtsK was assessed, and therefore, CtsK expression levels were measured in the TRAP-overexpressing breast cancer cell line MDA-MB-231 and the corresponding mock control cells." (PMID 32188406, 2020). "The presence of mRNA for each protease was clearly evident in H1975, HT29, MDA-MB-231, PANC1, and PC3 cell line, with the exception of cathepsin K, for which the expression was almost negligible in the MDA-MB-231 breast carcinoma cell line." (PMID 29560748, 2018). "Cathepsin K (CTSK), is a protease that is secreted from both metastatic breast cancer cells and osteoclasts to promote degradation of the bone matrix." (PMID 29805773, 2018). "In the case of cathepsins, CTSB, CTSD, CTSK, CTSL, and CTSS were expressed in all breast cancer cells; however, the mRNA and protein expression of CTSS was much higher in the TNBC cell lines compared to the hormone-responsive cell lines." (PMID 30185799, 2018).
breast carcinoma (continued). "Of note, NME2 is an upstream regulator of CTSK, a protease primarily expressed in osteoclasts which is involved in ECM degradation and bone remodeling and has been found to be expressed in numerous cancers including breast carcinoma." (PMID 39939916, 2025). "One of the molecular mechanisms through which cathepsin K contributes to breast cancer progression is by activation of ECM degrading matrix metalloproteinases, which enhances the invasiveness and metastatic capacity of breast cancer cells." (PMID 36002710, 2023). "In mouse models of breast cancer bone metastases established by injection of human MDA-MB-231 breast cancer cells, expression of osteolytic factors (RANKL, Cathepsin-K, and MMP9) was higher in ovariectomized (OVX) mice mimicking the postmenopausal bone microenvironment, compared with sham operation." (PMID 36419084, 2022). "LBDE has been reported to suppress breast cancer metastases and bone microenvironment by inhibiting the parathyroid hormone-related protein (PTHrP), matrix metallopeptidase 9 (MMP-9) and cathepsin K activities in breast cancer cells and osteoclastic bone resorption." (PMID 32046692, 2020). "LIPUS treatment was able to decrease the capability of breast cancer cell culture medium to induce osteoclastic differentiation in Raw264.7, showing a significant reduction of multinucleate TRAP+ cells,as well as CTSK and MMP9 expression and release, using both direct and indirect approaches." (PMID 30126457, 2018). "Meanwhile, the intraosseous mRNA levels of TRAP and CTSK in OBM patients was also higher than those in breast cancer patients without OBM and cancer-free individuals, respectively." (PMID 28071724, 2017). "Moreover, through co-culture experiments, we show that platelets activated by cathepsin K mediated the up-regulation of SHH, PTHrP, OPN, and TGFβ in epithelial-mesenchymal-like cells from patients with Luminal B breast cancer." (PMID 26931461, 2016). "Breast cancer comprises clinically and molecularly distinct tumor subgroups that differ in cell histology and biology and show divergent clinical phenotypes that impede phase III trials, such as those utilizing cathepsin K inhibitors." (PMID 26931461, 2016). "Because CTSK is coexpressed with FOXF2 and the CTSK proximal promoter region contains three putative FOXF2-binding sequences, we speculated that FOXF2 may enable breast cancer cells to induce osteoclast maturation by increasing CTSK." (PMID 31222004, 2019). "To further investigate the role of the FOXF2-CTSK axis in the interaction of breast cancer cells with bone, we performed bone-matrix invasion assays to test whether FOXF2-regulated CTSK secretion by cancer cells led to the degradation and invasion of the bone matrix." (PMID 31222004, 2019). "Cathepsin K-negative MGCs have also been reported in human breast carcinoma and lung biopsies." (PMID 26311062, 2015). "15d-PGJ2 also suppressed the RANKL/OPG ratio in osteoblastic cells exposed to breast cancer cell-derived osteolytic factors, the RANKL-induced differentiation of osteoclast precursors, and the formation of resorbed pits by decreasing the activities of cathepsin K and MMPs." (PMID 25859665, 2015). "Hence, CtsK is not necessary for cleaving TRAP 5a to TRAP 5b in breast cancer cells." (PMID 32188406, 2020). "Notwithstanding, CtsK was shown to be colocalized with TRAP and to be involved in the regulation of secretion of TRAP 5a in a breast cancer cell line, while it still was not essential for processing of TRAP 5a to TRAP 5b isoform." (PMID 32188406, 2020).
periodontitis (34 papers, 2014 to 2026). An acute or chronic inflammatory process that affects the tissues that surround and support the teeth. "CONCLUSION: Within the limitations of this study, vitamin D deficiency appeared to be associated with higher Cathepsin K levels in gingival crevicular fluid and saliva, particularly among individuals with periodontitis." (PMID 41501806, 2026). "In experimental periodontitis models, inhibition of cathepsin K caused an enormous drop in immune cell infiltration as well as a considerable decline in osteoclasts, macrophages, dendritic cells, and T cells." (PMID 37334378, 2023). "Cathepsin K deficient mice were protected both for developing rheumatoid arthritis and periodontitis." (PMID 29163477, 2017). "The role of cathepsin K in periodontal bone resorption is supported by studies in animal models of periodontitis showing reduced bone lesion in cathepsin K knockout mice, in shRNA-induced cathepsin K-deficient mice, and in mice treated with selective cathepsin K inhibitors." (PMID 41357757, 2025). "Therefore, local delivery of CtsK inhibitors may minimize adverse effects associated with this class of drugs and provide new treatment options for bone loss in periodontitis." (PMID 35757898, 2022). "Inhibiting CTSK could prevent inflammation and bone erosion caused by periodontitis, but it remains unclear whether the damaged alveolar bone caused by periodontitis can be regenerated by CTSK." (PMID 36386169, 2022). "Together, these studies highlight the predominant role of osteoclast-derived cathepsin K plays in periodontitis." (PMID 41357757, 2025). "In particular, inhibition of cathepsin K by VBX1000 was associated with an improvement in periodontal status regarding gingivitis (BIP) and periodontitis (CAL, PPD, and alveolar bone defect)." (PMID 41357757, 2025). "Odanacatib, a specific inhibitor of cathepsin K, has shown preliminary therapeutic promise in periodontitis models." (PMID 41459503, 2025). "In humans, cathepsin K in the gingival crevicular fluid of patients with periodontitis is elevated compared with healthy individuals, reflecting increased osteoclastic activity in periodontal tissues." (PMID 41357757, 2025). "The mechanism of action and the relative contribution of cathepsin K activity in the development of gingivitis and periodontitis remains poorly described." (PMID 41357757, 2025). "Several studies have suggested that cathepsin K likely plays a crucial role in alveolar bone resorption in patients with periodontitis." (PMID 41357757, 2025). ",17, 18, 19, 20, 21 Studies on the molecular mechanisms of periodontitis have found that elevated concentrations of CTSK in GCF are positively correlated with the severity of periodontitis." (PMID 40315697, 2025). "Below we summarize the observations in three different protease knockout mouse models, those with the following genes knocked out: Mmp-8, Cathepsin K, and plasminogen in periodontitis mouse models." (PMID 29163477, 2017). "To evaluate the effect of IFX on osteoclast formation in type 1 diabetes with periodontitis, we counted cathepsin K-positive multinucleated cells in the distal area." (PMID 29240821, 2017). "Cluster 4 contained 10 genes that were positively correlated with both MMP9 and CTSK in periodontitis." (PMID 27486459, 2016). "Cluster 2 genes (n = 12) were positively correlated with the expression of MMP2 and CTSK in both health and periodontitis, as well as with MMP9 only in periodontitis." (PMID 27486459, 2016). "Cluster 3 was a subset with 14 genes that negatively correlated with MMP2 in healthy samples and positively correlated with MMP9, RANKL, and CTSK in only the periodontitis samples." (PMID 27486459, 2016). "Cluster 5 genes (n = 34) showed a positive correlation with MMP9, RANKL, and CTSK in both healthy and periodontitis tissues, and a positive correlation with TNFα, but only in the healthy tissues." (PMID 27486459, 2016).